PLK1 (polo like kinase 1)
Diseases named in the same sentence as PLK1 in open-access papers (continued):
Sharing a sentence is not in itself a finding about the gene and the disease.
ovarian carcinoma (continued). "However, in platinum-resistant or refractory ovarian cancer, clinical trials of PLK1 inhibitors such as volasertib have demonstrated only modest efficacy, with progression-free survival not superior to chemotherapy and frequent hematologic toxicities as the principal dose-limiting events." (PMID 41354716, 2025). "Furthermore, in vivo delivery of αHer‐CrNC in a HER2‐positive ovarian cancer model could substantially suppress tumor growth, mediated by disruption of the plk1 gene and cellular apoptosis in the tumors." (PMID 38552157, 2024). "Indirect evidence for the tumor-promoting effect of overexpressed PLK1 in (relapsed) ovarian cancer comes from the induction of synthetic lethality in a patient-derived ovarian cancer cell culture and from the clinically approved antitumor effect of the PLK1 inhibitor B16727 (Volasertib®)." (PMID 34065956, 2021). "We then sought to examine how PLK1 might affect FBW7 levels in ovarian cancer cells." (PMID 29899826, 2018). "Thus, targeting Cyclin E1 by a PLK1 inhibition-based stabilization of FBW7 might be a novel approach to increase apoptosis in CCNE1-amplified ovarian cancer cells." (PMID 29899826, 2018). "Additionally, silencing of Chk1 and PLK1 could enhance radiation-or cisplatin-induced cytotoxicity in human ovarian cancer cells." (PMID 22246341, 2012). "Here, we evaluated the efficacy of the PLK1 inhibitor, volasertib, and the WEE1 inhibitor, adavosertib, along with the biomarker potential of cyclin E1 in ovarian cancer cells." (PMID 39994376, 2025). "The topmost ranked genes uncovered for the PD doublets include CDCA3, PLK1, NEK2 and FAM64A, which are involved in ovarian cancer cell proliferation and drug resistance." (PMID 40280979, 2025). "Given the roles of PLK1 in the DDR pathway, the aim of the present work was to explore the effect of onvansertib alone or in combination with olaparib in olaparib-resistant ovarian cancer preclinical models." (PMID 39039067, 2024). "Our results shed new light on the critical role of PLK1 in reversing PARPi resistance in KRAS-amplified HGSOC, and offer a new therapeutic strategy for this class of ovarian cancer patients where only limited options currently exist." (PMID 36142803, 2022). "Importantly, pharmacological induction of strong mitotic arrest via PLK1 inhibition and microtubule targeting followed by blocking mitotic exit activates apoptosis, prevents endoduplication and reduces chromosomal instability in an ovarian cancer cell line culture system." (PMID 34065956, 2021). "Studies have shown that inhibiting PLK1 in the presence of PTX resensitized ovarian cancer cells to PTX and reduced cell proliferation, as well as inducing apoptosis in HGSOC cells with CCNE1 amplification." (PMID 33182737, 2020). "Here we show that Aurora Borealis (BORA), a mitotic protein that plays a key role in activating the master mitotic kinase polo-like kinase 1 (PLK1), has an oncogenic role in ovarian cancer." (PMID 32268485, 2020). "We identified a novel combinatorial approach of paclitaxel and the small molecule inhibitor of PLK1, BI6727, to induce growth inhibition and apoptosis in ovarian cancer cell lines with CCNE1-amplification." (PMID 29899826, 2018). "To validate the GSEA results, we then detected the expression of cell cycle (PCNA and PLK1), DNA replication (MCM2 and MCM3) and BER pathways-related proteins (PARP1 and PARP2) in ovarian cancer cells transiently overexpressed ARHGAP10." (PMID 27010858, 2016). "PLK1 inhibitor, BI6727 (volasertib) is currently registered in 20 different clinical trials, and one study in ovarian cancer has been completed (NCT01121406)." (PMID 27558154, 2016).
ovarian carcinoma (continued). "In this study, the expression of PLK1 and PLK3 was determined immunohistochemically in tissue specimen of normal ovaries (n=9), cystadenomas (n=17), borderline tumours (n=13) and ovarian carcinomas (n=77)." (PMID 14970859, 2004). "For PLK1 and PLK3 expression, statistical correlation analysis with several clinicopathological factors was performed including all cases of primary ovarian carcinoma (n=77)." (PMID 14970859, 2004). "In 2008, a phase I clinical trial involving 20 cancer patients (3 with ovarian cancer) evaluated the potential antitumor activity of Rigosertib, the only non-ATP competitor PLK1 inhibitor that is also a known RAS inhibitor and PI3K inhibitor." (PMID 41458961, 2025). "The expression of PLK1, a key regulator of cell cycle progression and a marker of cellular proliferation, was inversely correlated with the vector-prone increase in DAPK1 re-expression, supporting an anti-proliferative role of DAPK1 in ovarian cancer." (PMID 40563561, 2025). "XST-20 (25 and 50 μM) significantly reduced the protein level of CCNB1 and PLK1 while FOXM1 protein level was not changed in three ovarian cancer cell lines." (PMID 35680842, 2022). "Next, we investigated whether blocking PLK1 and PARP would enhance Carboplatin response of 3D-primary spheroid cultures derived from two different patients diagnosed with ovarian cancer." (PMID 36142803, 2022). "The results of the current study show that PLK1 and AURKC are expressed in ovarian cancer cells." (PMID 33257688, 2020). "The expression of PLK1 and PLK3 was elevated in a fraction of cystadenomas and was even higher in the group of primary ovarian carcinomas, whereas borderline tumours tended to express lower levels of PLK1 and PLK3 compared to other epithelial tumour entities of the ovary." (PMID 14970859, 2004). "In a subgroup of ovarian carcinomas (n=54) in which data on KI-67 expression were available, a significant positive correlation of PLK1/PLK3-positive tumours towards higher KI-67 indices in comparison to PLK1/PLK3-negative tumours was observed." (PMID 14970859, 2004). "Accordingly, we investigated the effects of PLK1 and WEE1 inhibition in BRCA-WT and BRCA-Mut HGSOC models, focusing on DNA repair dependency, cell cycle regulation, and differential drug sensitivity, to identify therapeutic strategies for BRCA-WT and HRP ovarian cancers." (PMID 41354716, 2025). "In a pan-cancer analysis using mRNA quantitative sequencing data, however, differing correlations between PLK1 upregulation and overall survival of patients suffering from different cancer entities have been shown with PLK1 overexpression not influencing overall survival for ovarian cancer." (PMID 34065956, 2021).
glioma (55 papers, 2010 to 2025). A benign or malignant brain and spinal cord tumor that arises from glial cells (astrocytes, oligodendrocytes, ependymal cells). "The COVID-19 dataset showed enrichment in the PLK1 pathway, associated with stem cell cancer, glioma, and lung adenocarcinoma." (PMID 38601162, 2024). "Clinically, TRIM26 expression shows a direct correlation with GPX4 and PLK1 levels in glioma samples and is associated with poor outcome in patients with glioma." (PMID 37872147, 2023). "We also investigated the association between PLK1 expression and the histology of glioma in the genomic datasets." (PMID 36805592, 2023). "The co-deletion of 1p/19q was significant, and the IDH mutation rate was up to 75% in glioma with PLK1 low expression." (PMID 36618405, 2022). "In the survival analysis of primary glioma samples, the lower levels of PLK1 methylation were associated with poorer prognosis." (PMID 36618405, 2022). "The results indicated that the levels of PLK1 methylation were negatively associated with the WHO grade of glioma." (PMID 36618405, 2022). "The results showed that PLK1 expression levels were positively associated with glioma grades CGGA and TCGA databases." (PMID 36618405, 2022). "In the CGGA-325, CGGA-693, and TCGA datasets, high PLK1 mRNA levels were associated with shorter OS in pan-glioma and HGG patients." (PMID 36618405, 2022). "The high level of PLK1 has been associated with lower disease-free and overall survival rates, and poor prognostic factors for glioma patients." (PMID 34680264, 2021). "Furthermore, we observed that knocking down IQGAP3 leads to reduced expression of proteins associated with the PLK1/PI3K/AKT pathway in glioma cells." (PMID 38560572, 2024). "Besides, PPARG is the most significant gene is responsible for all of these diseases and our shared hub genes AURKB and PLK1 are associated with the disease, respectively, stomach neoplasms and glioma." (PMID 38717954, 2024). "To remedy this deficiency, we conducted an analysis of PLK1 in glioma immune regulation." (PMID 36618405, 2022). "Moreover, the glioma tissues showed distinct somatic mutations and CNVs based on the expression levels of PLK1." (PMID 36618405, 2022). "In addition, to determine whether PLK1 expression levels were associated with specific genomic characteristics in gliomas, we performed copy number variation (CNV) and somatic mutation analysis using the TCGA dataset." (PMID 36618405, 2022). "Moreover, higher PLK1 mRNA levels were associated with poorer prognosis of glioma patients." (PMID 36618405, 2022). "But over-expression of RGC32 suppressed glioma cell growth, probably by forming a protein complex with polo-like kinase 1 (PLK1) and inducting cell cycle arrest at G2/M." (PMID 40740769, 2025). "Transfection of c-MYC into glioma cells with low c-MYC expression not only upregulated PLK1 expression but sensitized glioblastoma cells to volasertib." (PMID 41458961, 2025). "c-MYC amplification has also been shown to increase the sensitivity of PLK1 inhibitors in glioma and medulloblastoma." (PMID 41458961, 2025). "We show that ANC@RNP/crEGFR‐PLK1 nanomedicine mediated efficient dual gene targeting of EGFR and PLK1 oncogenes in glioma cells with enhanced anti‐tumor effect versus single crRNA targeting of oncogenes." (PMID 38943253, 2024). "Our Cas12a RNP gene‐editing nanosystem (abbreviated as ANC@RNP) achieved up to 30–60% double knock‐out of EGFR and PLK1 oncogenes in glioma cell lines." (PMID 38943253, 2024). "In vitro experiments showed that downregulation of IQGAP3 inhibits the proliferation and migration of glioma cells, with the PLK1/PI3K/AKT pathway potentially playing a crucial role in IQGAP3-mediated glioma progression." (PMID 38560572, 2024).
glioma (continued). "In summary, IQGAP3 likely plays a crucial role in initiating and progressing glioma through multiple cancer-related pathways, including the PLK1/PI3K/AKT pathway." (PMID 38560572, 2024). "We also quantified the protein expression levels of EGFR and PLK1 in the dissected glioma tissues by Western Blot." (PMID 38943253, 2024). "In glioma stem cells (GSCs), inhibiting PLK1 induces apoptosis and DNA damage by phosphorylating YBX1 at serine 174 and serine 176, impairing its nuclear translocation." (PMID 38255791, 2024). "Mitotic kinase Aurora-A is overexpressed in glioma cells, and its expression is reported to be correlated with patient outcome; furthermore, Plk1 activity was found to be elevated in CD133+ glioblastoma multiforme cells." (PMID 38716144, 2024). "Consistent with the objective response of PLK1 inhibition in a subset of refractory cancers, a combination of PLK1 inhibitor and temozolomide, an alkylating agent prodrug, shows synergistic cytotoxicity in glioma cells." (PMID 36980292, 2023). "The down-regulation of PLK1 at both mRNA and protein levels was able to inhibit growth, induce the arrest of the cell cycle in G2/M and increase glioma cell apoptosis." (PMID 37644431, 2023). "To study the expression of PLK1 in glioma and its relationship with the prognosis of patients, we analyzed the TCGA and CGGA databases." (PMID 36805592, 2023). "In terms of glioma subtypes, consistent with PLK1, YBX1 is highly expressed in classic and proneural subtypes." (PMID 36805592, 2023). "PLK1 inhibition led to ferroptosis in glioma cells by dephosphorylating TRIM26, further resulting in GPX4 degradation." (PMID 37872147, 2023). "Reassuringly, RNF8 expression is also significantly anti-correlated with that of PLK1 in multiple glioma datasets, supporting our CMA hit." (PMID 37468549, 2023). "Our results confirmed that the expression of PLK1 was higher in glioma tissues than in normal tissues and was negatively correlated with the patient’s prognosis." (PMID 36805592, 2023). "We found that the mRNA expression of PLK1 was higher in the proneural and classical subtypes of glioma than in the mesenchymal and neural subtypes." (PMID 36805592, 2023). "We also used the CGGA database to analyze the correlation between PLK1 methylation levels and survival of glioma patients." (PMID 36618405, 2022). "The same trend was observed between the expression of PLK1 and macrophages chemokines in TCGA dataset in glioma." (PMID 36618405, 2022). "Since our specialty was neuro-oncology, we subsequently conducted a detailed study on the relationship between PLK1 expression and prognosis in glioma." (PMID 36618405, 2022). "PLK1 inhibits M1 macrophages infiltration into glioma immune microenvironment and is a potential biomarker for glioma." (PMID 36618405, 2022). "As shown in the CGGA data resource, the contents of PLK1/2/3/4 rose as the World Health Organization (WHO) grades of glioma increased." (PMID 35256538, 2022). "Subsequent experiments confirmed that PLK1 knockdown inhibited the proliferation of glioma cells but increased the M1 macrophages infiltration and polarization." (PMID 36618405, 2022). "And flow cytometry and EdU assays have verified that PLK1 can accelerate cell cycle and stimulate cell proliferation in glioma cell lines." (PMID 36618405, 2022). "The qRT-PCR showed that PLK1 RNA expression levels in glioma cell lines were significantly higher than that in NHA cells, and the highest expression levels were found in U87 cells." (PMID 36618405, 2022). "RNA-seq of 100 glioma cases in our sample database discovered that glioma patients with high PLK1 level had poorer prognosis compared with patients with low PLK1 level, which was consistent with the results using CGGA and TCGA datasets." (PMID 36618405, 2022). "The correlation between PLK1 mRNA levels and the prognosis of patients with pan-glioma, LGG, and GBM was investigated using the CGGA and TCGA datasets." (PMID 36618405, 2022).
glioma (continued). "Next, we explored the correlation between gene alterations of characteristic molecules and PLK1 expression level in glioma." (PMID 36618405, 2022). "And 100 glioma samples collected from surgeries were obtained to further validate the correlation between PLK1 mRNA expression and glioma grades or prognosis." (PMID 36618405, 2022). "In this present study, we have comprehensively explored the PLK1 expression and its relationship with the prognosis of tumor patients in glioma across some datasets." (PMID 36618405, 2022). "Simultaneously, highly expressed PLK1 is significantly related to prognosis, histological and genetic features in glioma by analyzing public databases." (PMID 36618405, 2022). "Taking glioma as an example, the methylation level of PLK1 was negatively correlated with PLK1 expression level." (PMID 36618405, 2022). "What’s more, we also explored the potential molecular mechanisms of PLK1 aberrant expression by analyzing methylation of PLK1 DNA and ceRNA network in glioma." (PMID 36618405, 2022). "It has been reported that PLK1 inhibits glioma cell invasiveness and induces apoptosis in glioma cells." (PMID 36186436, 2022). "The present study confirmed that PLK1 is positively correlated with the malignant progression of gliomas." (PMID 35256538, 2022). "In glioma cells, knock-out of PLK1 by shRNA had an inhibitory effect on autophagy through phosphorylation of the mTORC1 substrate RPS6KB." (PMID 35719948, 2022). "That is, PLK1 promotes the malignant characteristics and progression of glioma by accelerating cell proliferation and inhibiting M1 macrophages infiltration and polarization." (PMID 36618405, 2022). "Recently, the combination of temozolomide and PLK1 inhibitor has shown synergistic cytotoxicity in glioma cells in vivo." (PMID 36123603, 2022). "The EdU, flow cytometry, and macrophage infiltration assays as well as xenograft animal experiments were performed to determine the relationship between PLK1 and glioma immune microenvironment in vivo and in vitro." (PMID 36618405, 2022). "To further elucidate the correlation between PLK1 and infiltration of immune cells, we performed a single-cell RNA-seq analysis to reveal the expression level of PLK1 in different cell clusters in the tumor microenvironment of gliomas." (PMID 36618405, 2022). "Some experiments such as flow cytometry and EdU also confirmed that aberrant expression of PLK1 lead to the occurrence and progression of glioma by regulating the cell cycle." (PMID 36618405, 2022). "Then, since our team specializes in glioma, we focused on the relationship between PLK1 mRNA levels and prognosis of patients with glioma." (PMID 36618405, 2022). "In order to investigate the effect of PLK1 on the TIM of glioma, we established mouse intracranial orthotopic implantation tumor model." (PMID 36618405, 2022). "Overall, our analysis showed that PLK1 was highly expressed and a potential prognostic biomarker in various cancers, especially in glioma." (PMID 36618405, 2022). "In vivo and in vitro experiments confirmed that PLK1 affected glioma progression and TIM by regulating the infiltration and polarization of M1 macrophages." (PMID 36618405, 2022). "Whereas, PLK1 protein in human cancer tissues was highest in thyroid cancer, while the expression in glioma tissues was moderate." (PMID 36618405, 2022). "Univariable and Multivariate proportional hazard Cox analysis showed that PLK1 was a prognostic biomarker for glioma." (PMID 36618405, 2022). "Functional experiments identified that overexpression of PLK1 promoted the cell proliferation, migration and invasion in glioma." (PMID 33976745, 2021). "This corroborates a prior report where PLK1 inhibition enhanced TMZ mediated glioma cell cytotoxicity in-vitro and reduced tumor growth in-vivo." (PMID 34680264, 2021).